RN7SL423P (RNA, 7SL, cytoplasmic 423, pseudogene)
Gene: Miscellaneous RNA gene on chromosome 2 (160,877,547 to 160,877,850, forward strand). Ensembl gene ENSG00000244372.
Homologues: Orthologues: chimpanzee Metazoa_SRP (99% identical), macaque Metazoa_SRP (94% identical). Paralogues in human: RN7SL1 (79% identical), RN7SL2 (79% identical), RN7SL3 (78% identical), RN7SL597P (78% identical), RN7SL448P (77% identical), RN7SL650P (77% identical), RN7SL732P (77% identical), RN7SL126P (77% identical), RN7SL322P (77% identical), RN7SL177P (76% identical), RN7SL63P (76% identical), RN7SL803P (76% identical), and 700 more.